LBP (lipopolysaccharide binding protein)
Diseases named in the same sentence as LBP in open-access papers (continued):
Sharing a sentence is not in itself a finding about the gene and the disease.
endotoxemia (66 papers, 2011 to 2026). "This low-grade endotoxemia is associated with increased secondary biomarkers of LPS exposure, including LPS binding protein (LBP) and soluble cluster of differentiation 14 (sCD14) alongside evidence of inflammation (e.g., increased interleukin [IL]-6)." (PMID 40863166, 2025). "Both LBP and sCD14 are present in plasma and can be used to approximate levels of endotoxemia, a state indexed by a higher ratio of LBP:sCD14, which is indicative of a predisposition to higher pro-inflammatory responses to endotoxins." (PMID 39568668, 2024). "The HFHS diet significantly increased plasma LPS levels (p < 0.05 vs. CT), together with the plasma LBP levels (p < 0.0001 vs. CT), as indicative of chronic low-grade inflammation (endotoxemia) associated with a dysbiotic gut microbiota composition." (PMID 36052065, 2022). "The LBP:sCD14 ratio is a comparatively more stable and reliable measure than LPS, and so may be a better indicator of associations between endotoxemia and cognition." (PMID 39568668, 2024). "Collectively, these data position intestinal barrier integrity as a proximal node linking fermented-food matrices to reduced endotoxemia (LPS/LBP), dampened hepatic TLR4–MyD88–NF-κB signaling, and improved insulin sensitivity." (PMID 41599407, 2026). "Serum LBP is proposed as a promising marker of increased intestinal permeability and an indirect indicator of endotoxemia." (PMID 41373509, 2025). "A sample of 162 healthy adults (25–65 years old) provided plasma, from which a measure of endotoxemia was determined [i.e., the ratio of lipopolysaccharide binding protein (LBP) to soluble cluster of differentiation 14 receptors (sCD14)]." (PMID 39568668, 2024). "LBP is an indirect marker of endotoxemia, predominantly released by hepatocytes triggered by LPS—the molecules of the outer membrane of Gram-negative bacteria." (PMID 39796152, 2024). "LPS binding protein (LBP) and soluble cluster of differentiation 14 (sCD14) are used as markers of LPS in serum, and can be considered markers of endotoxemia." (PMID 37095714, 2023). "Indices of endotoxemia, LBP, and FABP were significantly elevated in HCV-infected participants compared to uninfected young and elderly controls." (PMID 37626844, 2023). "In this study, we examined plasma from HCV-infected participants, and a small cohort who initiated DAA therapy, for indices of inflammation (IL-6, IP10, sCD163, sCD14) and endotoxemia (Endocab, LBP, FABP)." (PMID 37626844, 2023). "LBP, one of the acute-phase response proteins, is involved in LPS binding, and its levels are usually increased in endotoxemia along with changes in EndoCAb IgM and IgG levels." (PMID 38137490, 2023). "We found that this intervention resulted in a 14% increase in circulating LBP, a marker of endotoxemia; a 0.7% increase in body weight; 47% and 31% increases in IMCL in TA and SOL, respectively; and a 200% increase in IHL." (PMID 37373776, 2023). "Endotoxemia was assessed by measuringLBP andproinflammatory cytokine IL-1β in serum.Exposure to arsenate increased serum LBP levels relative to controlanimals at 15 and 30 mg/L As(V) concentrations (35–36%)." (PMID 37819996, 2023). "LBP and sCD14 are produced in response to bacterial translocation and are proposed markers of endotoxemia." (PMID 35622782, 2022). "Whereas sCD14 and LBP are elevated in response to endotoxemia, LPS‐neutralizing EndoCAbs are consumed and are thus reduced in enhanced endotoxin loads." (PMID 35478447, 2022). "Serum LBP of the mice in WD group was significantly higher than that of the mice in NC group reflecting a higher level of endotoxemia induced by the Western diet, which was lessened by L. mucosae A1 treatment." (PMID 32806628, 2020). "In several clinical settings, the long- term (72 h) plasma levels of LBP induced by transient endotoxemia appear to better reflect long-term exposure to LPS than does measuring LPS itself." (PMID 33488424, 2020).
endotoxemia (continued). "Only IgA21 significantly inhibited HFD-induced endotoxemia and significantly reduced serum LBP and TNF-a (P < 0.04 vs. HFD)." (PMID 31178854, 2019). "For marker of endotoxemia, serum endotoxin and LBP were measured using TNF-α and IL-6 levels as indices of systemic inflammation." (PMID 31178854, 2019). "Rats subjected to 4 h of brain death had higher serum levels of LPS and LPS-binding protein (LBP), as evidence of endotoxemia." (PMID 30873176, 2019). "In our study, intake of both batches of lingonberries led to reduced plasma levels of LBP, which indicates reduced endotoxemia compared to mice receiving HF diet." (PMID 27125264, 2016). "To summarize, chronic low-grade endotoxemia, as seen in the case of T1DM, was associated with decreased levels of LBP and EndoCAb and with elevated levels of TNF-α, IL-6, IL-1β and GM-CSF, indicating chronic inflammation." (PMID 26367738, 2015). "Indeed, several indicators of intestinal permeability (e.g., increased LPS, LBP, sCD14) are prospectively associated with CVD events, and greater postprandial endotoxemia is linked to development of type 2 diabetes." (PMID 40863166, 2025). "It was hypothesized that higher levels of endotoxemia, indexed by the LBP:sCD14 ratio, would correlate with worsened performance on cognitive tasks, especially those related to attention and executive function." (PMID 39568668, 2024). "Circulating LBP, a marker of endotoxemia, increased significantly by 14% after HCHFD." (PMID 37373776, 2023). "One study indicated that LBP could be transported from the systemic circulation to the intestinal epithelial basolateral and finally into the gut lumen during endotoxemia." (PMID 37480114, 2023). "Moreover, signs of endotoxemia are observed in the serumof As(V)-treated animals (increases in lipopolysaccharide-bindingprotein LBP and the proinflammatory cytokine IL-1β)." (PMID 37819996, 2023). "However, the assessment of LPS in serum or plasma has significant challenges, including its short half-life, and to overcome these limitations, the determination of LBP (a proxy for LPS) is considered to be a better biomarker for endotoxemia." (PMID 34948768, 2021). "We then determined the association between shift-work exposure and levels of circulating cytokines, C-reactive protein (CRP), primary LPS-responsive leukocytes (monocytes, lymphocytes, and neutrophils), and LBP (a proxy for LPS) as an indicator of low-grade systemic endotoxemia." (PMID 34948768, 2021). "We next compared the relative abundance of significantly different microbial groups, potentially involved in protective or triggering endotoxemia-related processes, in MetS-HP vs. MetS non-HP patients, as well as their association with plasma LBP values." (PMID 32183480, 2020). "Therefore, we measured the serum LBP levels to indirectly determine the effect of butyrate treatment on endotoxemia." (PMID 30186272, 2018). "We therefore adopted the more stable biomarkers LBP and EndoCab IgG as indicators of endotoxemia." (PMID 28216979, 2017). "Since LBP is rapidly induced by LPS and EndoCab IgG reflects the immune response to endotoxin core, these biomarkers measure acute/intermittent and chronic/persistent endotoxemia, respectively." (PMID 28216979, 2017). "In the current study, serum levels of LBP and EndoCab IgG were measured in biopsy-proven NAFLD patients and their correlation with the histological severity of NAFLD was assessed to clarify associations between endotoxemia and NASH development." (PMID 28216979, 2017). "In feces, Christensenella associated with T1D and correlated negatively with fecal acetate (Spearman r = -0.416, p<0.05), whereas Subdoligranulum correlated significantly with plasma markers of endotoxemia (LBP, r = 0.519, p<0.001) and inflammation (CRP, r = 0.362, p<0.05) in T1D." (PMID 29211757, 2017).
endotoxemia (continued). "Increased LBP and sCD14 levels in all patient groups might be due to transient or low-grade endotoxemia, which is under the detection limit of 3 EU/ml in the endotoxin assay." (PMID 27698480, 2016). "Selective removal of the LPS adaptor protein LBP might represent a future therapeutic option to prevent EC dysfunction and tissue fibrosis in endotoxemia-induced AKI." (PMID 25261195, 2014). "However, despite the disruption of intestinal AJC proteins and increased intestinal barrier by WTE and alcohol, we could not find evidence of systemic inflammation (normal serum cytokine) or endotoxemia (normal serum LBP)." (PMID 40464220, 2025). "This suggests that women may be less likely to show strong reactions, positive or negative, to endotoxemia, even in the face of a greater proinflammatory predisposition measured by heightened LBP:sCD14 ratios." (PMID 39568668, 2024). "Differently, when a greater LPS concentration fails to stimulate sufficient hepatic response and LBP synthesis/release, LPS clearance may be altered, thus prolonging and exacerbating the inflammatory cascade associated with endotoxemia." (PMID 38139003, 2023). "The rapid increase in rectal temperature, respiration rate, and circulating acute phase proteins (LBP, SAA, Hp) observed in our bovine model replicates the rapid and robust immune responses previously reported in other models of endotoxemia." (PMID 40458405, 2025). "In obese infertile men, circulating LPS-binding protein (LBP), a marker of endotoxemia, positively correlates with 8-OHdG in sperm DNA, suggesting a gut–ROS–sperm damage axis." (PMID 40649988, 2025). "T2D patients often exhibit chronically elevated levels of circulating lipopolysaccharide-binding protein (LBP) and soluble CD14, biomarkers that signal sustained low-grade endotoxemia." (PMID 40871736, 2025). "The circulating levels of lipopolysaccharide-binding protein (LBP), a marker of gut permeability and metabolic endotoxemia, were significantly decreased by RebD." (PMID 38321177, 2024). "Currently, the LPS-binding protein (LBP) is considered an accurate biomarker of LPS and endotoxemia." (PMID 38339096, 2024). "Both interventions lowered serum levels of LBP and I-FABP through AMPK activation, implying inhibited endotoxemia and improved intestinal barrier function." (PMID 39456503, 2024). "After HCHFD, levels of circulating lipopolysaccharide binding protein (LBP), a marker of endotoxemia, increased by 14%." (PMID 37373776, 2023). "Other markers of immune activation and bacterial translocation include lipopolysaccharide (LPS) binding protein (LBP), which has been used as a marker of endotoxemia." (PMID 36069443, 2022). "Another study showed that pomegranate capsule (900 mg) reduced lipopolysaccharide-binding protein (LBP) levels, a marker of endotoxemia, in 57 patients with colorectal cancer." (PMID 34796029, 2021). "Circulating levels of lipopolysaccharide-binding protein (LBP) and soluble cluster of differentiation 14 (sCD14) are recognized as clinical markers of endotoxemia." (PMID 32570947, 2020). "It has been reported in mice and rat models that males and ovariectomized females show higher levels of IL-6- and LPS-binding protein (LBP, that promotes a pro-inflammatory cellular response) after LPS-induced endotoxemia." (PMID 29925409, 2018). "Circulating LPS-binding protein (LBP) and anti-endotoxin core immunoglobulin G (EndoCab IgG) antibody are commercially available surrogate markers of endotoxemia." (PMID 28216979, 2017). "Circulating LPS-binding protein (LBP) and the anti-endotoxin core immunoglobulin G (EndoCab IgG) antibody are commercially available surrogate markers of endotoxemia that are more stable than LPS." (PMID 28216979, 2017). "Binding of LPS with LBP is the first step in activating the CD14:TLR4 pathogen recognition pathway, and even subclinical amounts of LPS in circulation are considered evidence of systemic endotoxemia." (PMID 40427905, 2025).
endotoxemia (continued). "Furthermore, now we have evidence that synbiotics improve key markers of endotoxemia: LPS, LPS:HDL ratio, and LBP, providing a potential mechanistic explanation of our observations." (PMID 39636391, 2025). "On the other hand, in this study, short-term HCHFD induced a significant increase in levels of circulating LBP, a marker of endotoxemia, and a non-significant increase in levels of CRP." (PMID 37373776, 2023). "Thus, both LPS-binding protein (LBP) and sCD14 are considered biomarkers of endotoxemia and intestinal permeability, which also alters the gut microbiota." (PMID 38045684, 2023). "Lipopolysaccharide-binding protein (LBP) is an essential lipid component of the external membrane of Gram-negative bacteria, which causes endotoxemia." (PMID 36079050, 2022). "LPS-binding protein (LBP) and soluble CD14 (sCD14) dimerize to bind to circulating LPS, and increased levels in the plasma are indicative of higher circulating LPS levels and endotoxemia, making these viable proxy measures for LPS." (PMID 31817899, 2019). "Thus, it is not clear whether increased LBP is to be seen as the result of systemic inflammation, LPS-induced endotoxemia, or both." (PMID 36875067, 2023). "Only a few human studies have focused on the effect of an OF on endotoxemia and, to our knowledge, no study has been performed to date in order to evaluate the impact of dietary fat intake on the postprandial kinetics of LBP and sCD14 in NW, overweight and obese men." (PMID 32570947, 2020). "HPep1 inhibited LPS binding to LBP and LPS-mediated TNF-α production in human PBMCs and mice with subclinical endotoxemia, although it is not a lipid A-binding peptide." (PMID 21660935, 2011). "However, as all of the men in this study were heathy, not experiencing any acute event likely to produce a bolus exposure to LPS, this pattern is unlikely to explain the lack of correlation between LBP and LAL quantified endotoxemia." (PMID 32599766, 2020). "Second, lipopolysaccharide (LPS) is a component in the outer membrane of gram-negative bacteria, and LPS-binding protein (LBP) is a type 1 acute-phase protein that binds to LPS to facilitate an immune response and is a well-accepted marker of intestinal barrier integrity and endotoxemia." (PMID 40464220, 2025).
COVID-19 (38 papers, 2020 to 2026). A disease caused by infection with severe acute respiratory syndrome coronavirus 2. "Markers such as lipopolysaccharide-binding protein (LBP), which indicate gut microbiota dysfunction, have been closely associated with respiratory failure in COVID-19 patients." (PMID 40051430, 2025). "Severe COVID-19 was associated with higher levels of intestinal barrier integrity marker (zonulin) and microbial translocation markers (β-glucan and lipopolysaccharide binding protein (LBP))." (PMID 37205106, 2023). "In COVID-19, plasma LBP correlates with inflammasome activation and gut permeability, suggesting a role in systemic inflammation." (PMID 40284260, 2025). "During the acute phase of COVID-19, the gut leakage marker Lipopolysaccharide Binding Protein (LBP) was found to be elevated in plasma samples and was associated with cardiovascular complications via the activation of inflammasomes." (PMID 38495940, 2024). "The levels of lipopolysaccharide-binding protein (LBP) and intestinal fatty acid-binding protein (iFABP), a marker of gut epithelial damage, were also significantly elevated in convalescent COVID-19 patients at M3." (PMID 36943669, 2023). "Lipopolysaccharide-binding protein and PEDF have previously been shown to be elevated in COVID-19-associated cardiovascular complications." (PMID 37047497, 2023). "Gut permeability markers such as LPS, LBP, zonulin and cCD14 have been shown to be higher in COVID-19 patients than healthy controls." (PMID 36335131, 2022). "Specifically, it has been shown that COVID-19 patients present significantly increased levels of circulating lipopolysaccharide (LPS) and lipopolysaccharide binding protein (LBP)." (PMID 35630492, 2022). "We observed higher levels of zonulin, LBP, and sCD14 during severe COVID-19 in this validation cohort." (PMID 34177935, 2021). "Plasma LBP and inflammasome activation markers were significantly increased in COVID-19 patients with cardiac involvement." (PMID 33139693, 2020). "Notably, C9 and LBP were repeatedly identified across WGCNA, DiNA, and differential expression analyses, underscoring their robust association with severe COVID-19-associated molecular network remodeling." (PMID 42193140, 2026). "Elevated LBP levels in CSF suggest anexacerbated inflammatory state in patients with COVID-19." (PMID 40584364, 2025). "The only marker of intestinal permeability that was statistically significant between these groups was LBP, where we observed considerably higher concentrations in COVID-19 patients who died compared to both healthy controls and patients who survived (P = 0.003 and P = 0.005, respectively)." (PMID 39345212, 2024). "Commensal bacteria such as these have been shown to play an important role in maintaining intestinal homeostasis, and given the markedly elevated LBP concentrations in COVID-19, their depletion along with the enrichment of opportunistic pathogens may reflect a damaged intestinal epithelium." (PMID 39345212, 2024). "Other acute-phase proteins, including C-reactive protein (CRP) and lipopolysaccharide-binding protein (LBP), were also significantly elevated in PLWH with COVID-19 compared with HCs." (PMID 40568587, 2025). "Similar responses were observed, with CRP, SAA, LBP, and A1AG increasing with infection, which compared favorably with previous COVID-19 publications." (PMID 38879593, 2024). "The key targets of Paxlovid against LUAD/COVID-19 were obtained through network pharmacology, the most important targets include IL6, IL12B, LBP." (PMID 36157452, 2022). "In line with the cytokine storm hypothesis, several acute phase proteins were elevated in serum of COVID-19 patients, such as CRP, Lipopolysaccharide Binding Protein (LBP), ORM1, and ORM2." (PMID 37739942, 2023). "In the other hand, CD14, LBP and LRG1 might indicate the progression of lung damage in COVID-19 patients." (PMID 35884998, 2022).
COVID-19 (continued). "investigating GI tract barrier integrity in COVID-19 patients, there was an increase in LBP without an increase in I-FABP indicative of enterocyte damage, suggesting that the epithelial barrier is disrupted by another means." (PMID 36032119, 2022). "Subsequently, Paxlovid was analyzed against the core targets of LUAD/COVID-19 (CXCL2, CCL2, IL12B, CSF3, LBP, IL6, CXCL10) and Paxlovid, and the results showed that IL-6, IL12B, LBP and Paxlovid could be combined." (PMID 36157452, 2022). "Compared with the controls, LBP and CCL25 were significantly increased in COVID-19 patients." (PMID 33139693, 2020). "Surprisingly, despite a tendency to a more severe clinical presentation of COVID-19 in PWH, we did not detect significant differences in LBP, sCD14, I-FABP, E-cadherin, and Zonulin levels between the two groups." (PMID 40338851, 2025).